SPDYE6 (speedy/RINGO cell cycle regulator family member E6)
Tractability: No criterion of Open Targets' tractability assessment is met for any kind of drug.
Gene: Protein-coding gene on chromosome 7 (102,345,746 to 102,356,444, reverse strand). Ensembl gene ENSG00000260097.
Gene Ontology:
Molecular function: protein binding; protein kinase binding
Genetic constraint (gnomAD): Loss-of-function variants: 0 observed, 9.86 expected, observed/expected ratio (o/e) 0, 90% interval 0 to 0.3. That is too few expected variants to judge how well the gene tolerates losing a copy. Missense variants: 4 observed, 119.44 expected, observed/expected ratio (o/e) 0.0335, 90% interval 0.016 to 0.077. Synonymous variants: 2 observed, 41.16 expected, observed/expected ratio (o/e) 0.0486, 90% interval 0.019 to 0.15.
Homologues: Orthologues: chimpanzee SPDYE6 (88% identical), mouse Spdye4a (33% identical), rat Spdye4 (33% identical), mouse Spdye4b (29% identical). Paralogues in human: SPDYE2B (99% identical), SPDYE2 (99% identical), SPDYE5 (96% identical), SPDYE21 (94% identical), SPDYE1 (89% identical), SPDYE18 (82% identical), SPDYE16 (81% identical), SPDYE3 (62% identical), SPDYE12 (55% identical), SPDYE13 (55% identical), SPDYE14 (55% identical), SPDYE15 (55% identical), and 6 more.
Diseases named in the same sentence as SPDYE6 in open-access papers:
SPDYE6 is named in the same sentence as 2 diseases in open-access papers, as found by Europe PMC text mining. Sharing a sentence is not in itself a finding about the gene and the disease. The quoted sentences say what the papers report.
asthma (1 paper, 2020). "A similar situation was found in a novel lncRNA MSTRG.18506.1 which interacts with three asthma-related genes, i.e., SPDYE6, ATF7IP, VPS37A." (PMID 32948203, 2020). "Notably, LINC02145 exhibited to be correlated to six asthma-related genes, including ZFN19, G2E3, ATF7IP, PEA15, SPDYE6, VWA5A." (PMID 32948203, 2020).
insomnia (1 paper, 2022). A sleep disorder characterized by difficulty in falling asleep and/or remaining asleep. "The SPDYE1 gene has no previous association to measures of sleep patterns and very little description of CNVs at this location; however, a related gene, SPDYE6, has been associated with insomnia via SNP GWAS in a much larger sample set (1.3 million samples)." (PMID 36779085, 2022).